LOXL2 (lysyl oxidase like 2)
Diseases named in the same sentence as LOXL2 in open-access papers (continued):
Sharing a sentence is not in itself a finding about the gene and the disease.
amyotrophic lateral sclerosis (1 paper, 2022). Amyotrophic lateral sclerosis (ALS) is a neurodegenerative disease characterized by progressive muscular paralysis reflecting degeneration of motor neurons in the primary motor cortex, corticospinal tracts, brainstem and spinal cord. "A study about amyotrophic lateral sclerosis (ALS) demonstrated that the expression of LOXL2 was significantly up‐regulated in gastrocnemius muscle of model group, suggesting that LOXL2 may be involved in the early neuromuscular abnormalities of ALS." (PMID 35712918, 2022).
astrocytomas (1 paper, 2022). "LOXL1, LOXL2, LOXL3, and LOXL4 expression levels were also found to increase progressively in astrocytomas from grades 2 to 4, proving highest in GBM, and significantly higher relative to non-neoplastic brain tissue." (PMID 36076905, 2022). "Gene expression analysis by quantitative real-time PCR (RT-qPCR) for LOX, LOXL1, LOXL2, LOXL3, and LOXL4 showed increased expression levels in astrocytoma samples compared to non-neoplastic (NN) samples." (PMID 36076905, 2022).
bone tumors (1 paper, 2020). "Decreased Loxl2 was also observed in WlsΔOB-OS bone tumors by IHC, regardless whether wls was inactivated preventively (at 3 weeks) or therapeutically (at 5 weeks)." (PMID 32686768, 2020).
cardiac arrhythmia (1 paper, 2022). Any disturbances of the normal rhythmic beating of the heart or MYOCARDIAL CONTRACTION. "Loxl2 inhibition concurrently reduced age-related cardiac arrythmia and collagen (Pericardin) fiber width." (PMID 34734976, 2022). "To test if Loxl2 reduction could affect the Drosophila heart we made use of the SOHA software, to measure cardiac arrhythmia indices; which can be used as measures of heart health and cardiac aging." (PMID 34734976, 2022).
cervical squamous cell carcinoma (1 paper, 2020). A squamous cell carcinoma arising from the cervical epithelium. "To demonstrate the correlation between LOXL2 expression and DNA methylation of the LOXL2 promoter, we performed integrated visualization of LOXL2 expression and DNA methylation data in MEXPRESS based on 317 cervical squamous cell carcinomas and endocervical adenocarcinomas from TCGA." (PMID 32211324, 2020).
chondroblastic osteosarcoma (1 paper, 2024). An osteosarcoma characterized by the presence of atypical cartilage of variable cellularity. "Chondroblastic osteosarcoma contains a unique cluster (Cos) expressing genes associated with hypertrophic chondrocyte differentiation; COL10, SOX9, and LOXL2." (PMID 38267611, 2024).
chronic asthma (1 paper, 2024). An asthma that is characterized by the development of persistent airway inflammation and recurrent attacks of breathlessness and wheezing, which vary in severity and frequency. "In order to explore the potential functions of LOXL2 in chronic asthma models, lentiviral shRNA vectors targeting LOXL2 were constructed and injected into mice through tail vein." (PMID 38824593, 2024). "We further confirm the expression level and location of LOXL2 in the OVA-induced chronic asthma models." (PMID 38824593, 2024). "Remarkably, biological process of cell-cell adhesion, one of the early and core changes during EMT, was also significantly affected after LOXL2 knockdown in chronic asthma models." (PMID 38824593, 2024).
clubfoot (1 paper, 2022). The most common congenital deformation of the foot, occurring in 1 of 1,000 live births. "We observed a significant increase in the positivity of LOX and LOXL2 (two of the main LOXs) in the contracted tissue (M-side) of the relapsed clubfoot in comparison with non-contracted tissue by IHC." (PMID 35292718, 2022).
ductal carcinoma (1 paper, 2021). "OSM signaling and LOXL2 nuclear localization have been implicated in promoting epithelial to mesenchymal transition in ductal carcinoma cells." (PMID 34011405, 2021). "Due to the alignment of collagen I fibers, it is expected that OSM-induced LOXL2 will promote ductal carcinoma cell invasion and metastasis as tumor cells migrate along aligned collagen fibers." (PMID 34011405, 2021). "Taken together, these results demonstrate that OSM induces sufficient LOXL2 protein expression/secretion to promote remodeling and alignment of collagen I fibers in the ductal carcinoma tumor microenvironment." (PMID 34011405, 2021).
dysplasia (1 paper, 2019). A usually neoplastic transformation of the cell, associated with altered architectural tissue patterns. "In dysplasia, LOXL2 and LOX were highly expressed in the outer keratinized oral epithelium, with some staining observed extending into the stratum spinosum." (PMID 31086173, 2019).
emphysema (1 paper, 2006). "Fifteen genes were thus found to be upregulated in fibroblasts of emphysema, among them IGFBP-rP1 (4.9-fold), LOX (3.3-fold), LOXL2 (3.9-fold) and TIMP3 (3.0-fold), whereas 121 genes were downregulated, among them CDK4 (6.3-fold), FOSL1 (4.8-fold), OAZ1 (6.7-fold) and IGFBP-5 (5.3-fold)." (PMID 16504044, 2006).
endometrioid ovarian carcinoma (1 paper, 2020). "When considering endometrioid ovarian carcinoma patients, the mRNA expression levels of LOX, LOXL1, LOXL2, LOXL3, and LOXL4 demonstrated no relation with OS or PFS." (PMID 33058284, 2020).
endometriosis (1 paper, 2022). The growth of functional endometrial tissue in anatomic sites outside the uterine body. "This indicates that LOXL2 is a protein secreted from various tissues, and higher serum LOXL2 in PID with pelvic adhesion suggests that LOXL2 might also be highly expressed in endometrium and fallopian tube, which is supported by a study in endometriosis." (PMID 35246120, 2022).
esophageal tumor (1 paper, 2022). "Here, we found that LOXL2 and its catalytically inactive L2Δ13 splice variant boost glucose metabolism of esophageal tumor cells, facilitate tumor cell proliferation and promote tumor development in vivo." (PMID 36209516, 2022).
glomerular disease (1 paper, 2018). "By demonstrating that LOXL2 inhibition modifies ECM in diseased glomeruli we have strengthened the evidence for LOXL2 to be involved in the glomerular disease process." (PMID 29930330, 2018).
glomerulosclerosis (1 paper, 2018). A hardening of the kidney glomerulus caused by scarring of the blood vessels. "The amelioration of glomerulosclerosis and proteinuria in this model by selective LOXL2 inhibition with PXS-S2B appears to be an indicator that this vicious cycle can be successfully interrupted." (PMID 29930330, 2018). "The present study shows an attenuation of glomerulosclerosis and albuminuria as well as a reduction in glomerular fibronectin with the LOXL2 inhibitor treatment, indicating a protective effect in the glomerulus." (PMID 29930330, 2018). "The glomerulosclerosis index was further reduced when the treatment with the LOXL2 inhibitor and telmisartan was combined (p < 0.01)." (PMID 29930330, 2018). "Diabetic mice treated with the LOXL2 inhibitor had significant reduction in the glomerulosclerosis score (P < 0.05 vs. DM), whereas the reduction in the telmisartan group was statistically not significant." (PMID 29930330, 2018). "Diabetic animals treated with the LOXL2 inhibitor had lower albuminuria and ameliorated glomerulosclerosis with reduced cortical ECM markers." (PMID 29930330, 2018). "The inhibition of LOXL2 with a novel small molecule LOXL2 inhibitior was well tolerated and lead to the amelioration of glomerulosclerosis and proteinuria." (PMID 29930330, 2018). "Diabetic mice had albuminuria, higher glomerulosclerosis scores, upregulation of fibrosis markers and increased renal cortical LOXL2 expression." (PMID 29930330, 2018).
Infertility (1 paper, 2022). "There LOXL2 may be a good serum biomarker for PID patients with high risk of pelvic adhesion and infertility." (PMID 35246120, 2022).
injury (1 paper, 2018). Damage inflicted on the body as the direct or indirect result of an external force, with or without disruption of structural continuity. "A recent study showed that lysyl oxidase-like protein 2 (LOXL2) produced by reactive BECs, portal myofibroblasts, and Kupffer cells repressed E-cadherin expression and disrupted the barrier function of BECs through Snail activation, resulting in aggravation of cholestatic liver injury in mice." (PMID 29895797, 2018).
invasive carcinoma (1 paper, 2004). A carcinoma that is not confined to the epithelium, and has spread to the surrounding stroma. "In contrast, LOXL2 mRNA was abundant in peritumoral fibroblasts around invasive carcinomas (45 out of 106, 42% positive)." (PMID 14737219, 2004).
keloid (1 paper, 2021). An irregularly shaped, elevated mark on the skin caused by deposits of excessive amounts of collagen during wound healing. "In addition to collagen-degrading enzymes, we examined the gene-expression levels of collagen-cross-linking enzymes, such as LOX, LOXL-1, LOXL-2 and LOXL-3, finding that they were substantially upregulated in keloid dermal fibroblasts relative to either normal or hypertrophic dermal fibroblasts." (PMID 33672186, 2021).
left ventricular hypertrophy (1 paper, 2022). Enlargement of the LEFT VENTRICLE of the heart. "The gene expression of LOXL2 is increased in cardiac tissue of spontaneously hypertensive rats with left ventricular hypertrophy." (PMID 36159334, 2022).
liver cirrhosis (1 paper, 2017). "The analysis showed that except Lrat, which is also a marker for quiescent HSC, expression of Col1α(I), αSMA, and LOXL2 increased with accompanying liver cirrhosis in non-tumor site." (PMID 28465473, 2017).
malignant glioma (1 paper, 2025). A grade III or grade IV glioma arising from the central nervous system. "The results showed that LOXL2 was enriched in more malignant glioma subtypes and showed specific molecular characteristics in IDH wild type and 1p/19q uncodeleted subtypes." (PMID 40756111, 2025).
mesothelioma (1 paper, 2020). A usually malignant and aggressive neoplasm of the mesothelium which is often associated with exposure to asbestos. "However, four (LOX, LOXL1, LOXL2, LOXL4) and three (LOX, LOXL1, LOXL4) members were present in the mesothelioma (MESO; 87 patients, 239 genes) and ovarian serous cystadenocarcinoma (OV; 427 patients, 209 genes) datasets." (PMID 33383846, 2020).
neck cancers (1 paper, 2021). "High LOXL-2 expression in larger proportion of cases (72%) in the present study can be explained by the fact that there are alterations in the gene expression patterns of collagen crosslink associated enzymes in oral, head, and neck cancers." (PMID 33639646, 2021).
osteoporosis (1 paper, 2025). A condition of reduced bone mass, with decreased cortical thickness and a decrease in the number and size of the trabeculae of cancellous bone (but normal chemical composition), resulting in increased fracture incidence. "It showed that in osteoporosis patients, CP (P < 0.01), LIPT1 (P < 0.05), SLC25A3 (P < 0.001), and UBE2D3 (P < 0.01) were upregulated, while the expression levels of CDKN2A (P < 0.05), DBH (P < 0.01), DLST (P < 0.05), LOXL2 (P < 0.05), SLC31A1 (P < 0.05), and UBE2D1 (P < 0.01) were downregulated." (PMID 40980812, 2025).
paroxysmal AF (1 paper, 2017). "In addition, serum LOXL2 levels were increased in the patients with persistent AF (Ps-AF) than those patients with paroxysmal AF (Px-AF) (645.45 ± 301.37 pg/ml vs 434.54 ± 297.90 pg/ml, P<0.01)." (PMID 29089463, 2017).
pelvic inflammatory disease (1 paper, 2022). Pelvic inflammatory disease (PID) is an acute or chronic inflammation in the pelvic cavity. "Here, we aimed to analyze the correlation between serum LOXL2 and pelvic adhesion in chronic pelvic inflammatory disease (PID)." (PMID 35246120, 2022).
preeclampsia (1 paper, 2019). Preeclampsia is a hypertensive disorder of pregnancy that is characterized by new-onset hypertension with proteinuria presenting after 20 weeks of gestation, and depending on mild or severe forms may initially present with severe headache, visual disturbances, and hyperreflexia. "Overall, these findings indicate that collagen accumulation caused by the downregulation of LOX and LOXL2 may be a key factor in suppressing trophoblast cell migration and invasion in preeclampsia." (PMID 30804321, 2019). "Furthermore, evaluation of clinical samples revealed that downregulation of LOX and LOXL2 and upregulation of collagen were associated with preeclampsia." (PMID 30804321, 2019). "Here we revealed that lysyl oxidase (LOX) and LOX-like protein 2 (LOXL2) play a critical role in preeclampsia." (PMID 30804321, 2019). "Our results showed that both mRNA and protein expression of LOX and LOXL2 was decreased in placentas from patients with preeclampsia." (PMID 30804321, 2019). "Our study demonstrated that downregulation of LOX and LOXL2 is relevant to preeclampsia." (PMID 30804321, 2019). "Considering the localization of LOX proteins in trophoblasts from first-trimester villi and the downregulation of LOX and LOXL2 in preeclamptic placentas, we speculated that loss of function of LOX or LOXL2 in trophoblast cells is critical for preeclampsia." (PMID 30804321, 2019). "Collectively, our study suggests that the downregulation of LOX and LOXL2 leading to reduced trophoblast cell migration and invasion through activation of the TGF-β1/Smad3/collagen pathway is relevant to preeclampsia." (PMID 30804321, 2019). "Thus, we proposed that LOX, LOXL2, and the TGF-β1/Smad3/collagen pathway can serve as potential markers and targets for clinical diagnosis and therapy for preeclampsia." (PMID 30804321, 2019). "Thus, our findings suggest that LOX, LOXL2, and the TGF-β1/Smad3/collagen pathway are potential markers and targets for clinical diagnosis and therapy for preeclampsia." (PMID 30804321, 2019). "Thus, future research in uncovering direct LOX- and LOXL2-mediated molecules may provide deeper insights into the function of LOX and LOXL2 in preeclampsia." (PMID 30804321, 2019).
pulmonary hypertension (1 paper, 2022). Increased pressure within the pulmonary circulation due to lung or heart disorder. "Higher expression of LOXL2 has been found in hypoxia-exposed mice’s lungs, which developed pulmonary hypertension and showed increased collagen crosslinking right ventricular hypertrophy." (PMID 36159334, 2022). "Our results are by another report that LOXL2 inhibition by lysyl oxidase inhibitor, β-aminopropionitrile, attenuated right ventricular hypertrophy, and normalized collagen crosslinking in hypoxia-exposed pulmonary hypertension mice." (PMID 36159334, 2022).
rectal cancer (1 paper, 2025). A primary or metastatic malignant neoplasm that affects the rectum. "mIHC was performed on tumour specimens obtained from patients diagnosed with gastric and rectal cancer, aiming to investigate the association between the expression levels of LOX and LOXL2 and the presence of CAFs expressing α‐SMA, as well as TAMs expressing CD68 and CD206." (PMID 40179101, 2025). "Our results showed that in gastric and rectal cancer specimens, tumour areas with high expression of LOX and LOXL2 also exhibited significant expression of α‐SMA, a specific surface marker for CAFs." (PMID 40179101, 2025).
sarcoidosis (1 paper, 2022). Sarcoidosis is a multisystemic disorder of unknown cause characterized by the formation of immune granulomas in involved organs. "In our study, LOXL1 and LOXL4 showed increased expression in the IPF group, as well as LOXL2 and LOXL4 in the sarcoidosis group." (PMID 35203313, 2022).
sarcopenia (1 paper, 2022). Progressive decline in muscle mass due to aging which results in decreased functional capacity of muscles. "Taken together, these data indicate the possibility of using LOXL2 inhibitors to prevent aging‐related sarcopenia, especially with significant fibrosis." (PMID 35712918, 2022). "In vivo, LOXL2 inhibitor can reduce D‐gal‐induced skeletal muscle fibrosis, inhibit oxidative stress, promote the increase of skeletal muscle mass and strength which plays a protective role in sarcopenia." (PMID 35712918, 2022).
serous ovarian carcinoma (1 paper, 2020). "The results indicated that the overexpression of LOX, LOXL1, LOXL2, LOXL3, and LOXL4 mRNA in serous ovarian carcinoma patients was related to unfavorable OS and PFS." (PMID 33058284, 2020).
Stroke (1 paper, 2016). Sudden impairment of blood flow to a part of the brain due to occlusion or rupture of an artery to the brain. "Strikingly, the stroke work and plPwr were normalized, indicating that Loxl2 inhibition prevents stress-induced systolic abnormalities and restores cardiac contractile function to the sham control level." (PMID 27966531, 2016).
tongue tumors (1 paper, 2019). "IHC staining of PXS-S1C-treated mice demonstrated reduced Ki-67 staining (proliferation marker) compared to no inhibitor-treated control mice and lower expression of LOXL2 in tongue tumor samples in treated mice." (PMID 31086173, 2019). "IHC staining of the tongue tissues indicate that treatment of mice with LOXL2 inhibitor PXS-S1C decreased levels of PCNA and LOXL2 in LY2 tongue tumors." (PMID 31086173, 2019).
type 2 diabetes (1 paper, 2018). "In this study, we replicated five CpGs in blood, from which four reside in the genes previously shown to be associated with type 2 diabetes (ABCG1, LOXL2, SLC1A5, SREBF1)." (PMID 29164275, 2018). "In our Lifelines sample, five out of 52 included CpGs showed significant associations with type 2 diabetes (the Bonferroni-adjusted p < 0.0009 (0.05/52 CpGs)), including the loci in the ABCG1, LOXL2, TXNIP, SLC1A5 and SREBF1 genes (see a short description in ESM Box 1)." (PMID 29164275, 2018).
ulcerative colitis (1 paper, 2025). An inflammatory bowel disease involving the mucosal surface of the large intestine and rectum. "In conclusion, we identified a close association between COL1A1, LOXL2, VWF, MZB1, and ERS in the pathogenesis of ulcerative colitis (UC)." (PMID 40607383, 2025). "Through this approach, we demonstrated that COL1A1, LOXL2, and VWF may participate in the fibrotic pathological process of ulcerative colitis by regulating fibrosis-related pathways." (PMID 40607383, 2025).
uveal melanoma (1 paper, 2025). A melanoma derived from melanocytes of the uveal tract. "These uveal melanoma patients exhibit an increase in the expression of classic and well-documented hypoxia-dependent genes such as PDGFB, LOXL2, VEGF, ANGPT2, KDR, and S1PR1." (PMID 40000790, 2025).